RHO (rhodopsin)
Diseases named in the same sentence as RHO in open-access papers (continued):
Sharing a sentence is not in itself a finding about the gene and the disease.
retinal degeneration (continued). "Defects in rhodopsin biosynthesis and trafficking cause retinal degeneration in both Drosophila and humans; more than 120 mutations in the rhodopsin gene are associated with human retinitis pigmentosa." (PMID 25715730, 2015). "Among the mechanisms examined, the involvement of ER stress has been proposed as a common pathway in rod photoreceptor cell death in several animal models of retinal degeneration that carry different RHO mutations." (PMID 25695253, 2015). "The first mutation identified to cause retinal degeneration was Drosophila ninaE, which encode the major rhodopsin, Rh1." (PMID 26659849, 2015). "An association between light exposure and the initiation or exacerbation of retinal degeneration has been suggested to occur in a subset of RHO adRP mutations, and has been experimentally demonstrated in several animal models." (PMID 25695253, 2015). "The P23H mutant rhodopsin transgenic rat is an experimental model of retinal degeneration that exhibits gradual, fast photoreceptor loss with similar properties to human autosomal dominant retinitis pigmentosa." (PMID 25278831, 2014). "Mutations that prevent the N-glycosylation of Drosophila rhodopsin cause photoreceptor defects and retinal degeneration." (PMID 24785692, 2014). "In a mouse model overexpressing mutated human rhodopsin, retinal injections of a viral vector carrying an engineered ZF, coupled to a transcriptional repressor, reduced transcription levels of mutated rhodopsin and prevented retinal degeneration." (PMID 25100403, 2014). "25% overexpression of rhodopsin in the Bouse transgenic line on the WT (rds+/+) background has previously been shown to cause retinal degeneration." (PMID 24897172, 2014). "In fact, reduced rhodopsin content due to vitamin A deprivation or mutation in the rhodopsin gene rescued norpA-triggered retinal degeneration." (PMID 23754968, 2013). "Because of the high rate of rhodopsin mutations in RP patients, the present study was performed to confirm the protective effects of Tat-μCL against retinal degeneration in rhodopsin transgenic S334ter and P23H rats." (PMID 23951212, 2013). "The slow time course of retinal degeneration in rhodopsin-deficient mice was similar as in previous studies." (PMID 23468924, 2013). "A previous study found that the functional loss of the “granule group” genes resulted in rhodopsin accumulation in the Rab7-positive late endosomes and triggered retinal degeneration in norpA mutant photoreceptor cells." (PMID 23754968, 2013). "The loss of rdgC function leads to light- and age-dependent retinal degeneration as a result of excessive endocytosis of stable rhodopsin-arrestin complexes." (PMID 23754968, 2013). "More specifically, it was demonstrated that mutations in the pdh gene lead to a light-dependent loss of rhodopsin and retinal degeneration." (PMID 24058333, 2013). "Because of their genetic malleability, mice and rats provide the most common models with rhodopsin mutations, including P23H, T17M, P347S, and S334X, present on transgenes, leading to retinal degeneration at varying rates." (PMID 23077406, 2012). "Mutations in rhodopsin cause retinitis pigmentosa in humans and retinal degeneration in a multitude of other animals." (PMID 22276148, 2012). "In a transgenic mouse line, an excess of rhodopsin of only 23% was enough to cause RP-like retinal degeneration." (PMID 23077406, 2012). "The most common allele in North America for autosomal dominant retinitis pigmentosa, a major cause of retinal degeneration and vision loss worldwide, is a missense mutation (P23H) in the gene encoding rhodopsin." (PMID 22276148, 2012). "Numerous rhodopsin mutations were isolated in Drosophila screens in the late 1960s, many of which cause retinal degeneration in fly photoreceptors." (PMID 22194648, 2011).
retinal degeneration (continued). "Female transgenic mice expressing the VPP rhodopsin mutation, known to cause a retinal degeneration, were bred to male transgenic mice expressing the fat-1 gene, which can convert n6 to n3 polyunsaturated fatty acids (PUFA)." (PMID 20806040, 2010). "Activation of the UPR is most likely a protective response in retinitis pigmentosa because activating the UPR in Drosophila models of rhodopsin misfolding and retinal degeneration protects from photoreceptor loss." (PMID 20927324, 2010). "We show that Q344ter expressed at 24% of total rhodopsin caused a moderate rate of retinal degeneration in dark-reared mice, an experimental condition that isolated the effect of rhodopsin mislocalization." (PMID 20532191, 2010). "In summary, these results underscore the complex nature of retinal degeneration induced by rhodopsin mutations." (PMID 20532191, 2010). "Dark-reared Q344terrho+/− mice exhibited retinal degeneration, demonstrating that rhodopsin mislocalization caused photoreceptor cell death." (PMID 20532191, 2010). "Mutations in the human rhodopsin that affect its folding, trafficking and activity are the most commonly encountered causes of retinal degeneration in afflicted patients." (PMID 19214218, 2009). "Previous work using Drosophila as a model system and analysis of specific mutations in human rhodopsin have uncovered a connection between rhodopsin endocytosis and retinal degeneration." (PMID 19214218, 2009). "Mutations that affect the rhodopsin sorting signal interfere with interactions between Arf4 and rhodopsin, leading to an aberrant trafficking and the initiation of retinal degeneration." (PMID 17327826, 2007). "This was unexpected since retinal degeneration caused for example by rhodopsin mutations can be prevented by blocking apoptosis." (PMID 17592635, 2007). "Accordingly, mutations affecting either rhodopsin, ninaC or components involved in establishment of the microtubule network, i.e. F-actin capping proteins, cause a likewise retinal degeneration." (PMID 17592635, 2007). "RHO, the first gene identified in autosomal dominant RP, undergoes mutation-induced misfolding and mislocalization, leading to aberrant signal transduction and eventual retinal degeneration." (PMID 41805095, 2026). "Rhodopsin mutations lead to adRP, where defective rhodopsin proteins cause retinal degeneration." (PMID 41155961, 2025). "Mutations in the rhodopsin (RHO) gene, encoding the light-sensing visual pigment essential for phototransduction in rod photoreceptors, are a major cause of retinal degeneration, with the P23H change accounting for over 10% of autosomal dominant RP (adRP) cases in the US." (PMID 40231721, 2025). "Both the mechanism by which rhodopsin misfolding leads to rod photoreceptor cell death and whether all misfolding rhodopsin mutations cause retinal degeneration by a common mechanism is unclear." (PMID 39875362, 2025). "Additionally, expression of Arf4 mutant deficient in ASAP1-mediated GTP hydrolysis disrupted rhodopsin trafficking and caused retinal degeneration." (PMID 39774853, 2025). "For instance, RHO mutations primarily result in protein misfolding, which subsequently induces endoplasmic reticulum stress and ultimately leads to the demise of rod cells, thereby causing retinal degeneration." (PMID 39728691, 2024). "Mutations within rhodopsin are linked to several inherited retinal degenerations." (PMID 39556729, 2024). "Mutations in rhodopsin can cause it to misfold and lead to retinal degeneration." (PMID 38365903, 2024). "Mutations in rhodopsin can cause the receptor to aggregate, however, it is unclear whether this molecular defect underlies the retinal degeneration in autosomal dominant retinitis pigmentosa." (PMID 38365903, 2024). "In the current study, P23H and G188R rhodopsin mutations, both of which cause adRP16,32, were examined in vitro and in vivo to determine the possibility that aggregation of the receptor contributes to retinal degeneration." (PMID 38365903, 2024).
retinal degeneration (continued). "The progressive retinal pathologies in FUN025 mice differ from rapid retinal degeneration observed in mice with mutations in phosphodiesterase 6B (Pde6b), rhodopsin (Rho), and other genes linked with inherited retinal diseases in humans that is complete by two to three weeks of age." (PMID 38576540, 2024). "Thus, it seems that RPGR disease-causing variants are one of the most common causes of retinal degeneration in addition to rhodopsin (RHO) gene disease-causing variants." (PMID 37895299, 2023). "Thus, neurotrophic factors are promising candidates for the treatment of retinal degeneration related to rhodopsin mutations." (PMID 37077319, 2023). "Targeted gene therapy is promising for RHO-associated RP; however, it requires the inhibition of mutant RHO protein expression with simultaneously increasing the wild-type-to-mutant RHO ratio to effectively reduce the rate of retinal degeneration." (PMID 37712069, 2023). "Likewise, retinal health and homeostasis depend on several factors/processes, dysregulation of which, including defects in rhodopsin, lipid homeostasis and iron storage to name a few, have been implicated in retinal degeneration." (PMID 36952572, 2023). "To test whether similar consequences arise from retinal degeneration, we used RhoP23H mice that model the most common rhodopsin mutant in humans linked to retinal degeneration." (PMID 37961457, 2023). "Two rhodopsin mutations, Y102H and I307N, obtained in chemically mutagenized mice, are currently the subject of increased interest as relevant models for studying the process of retinal degeneration in humans." (PMID 34997336, 2022). "Interestingly, consistent with the improved rhodopsin shutoff kinetics, the retinal degeneration caused by this mutant was light-independent." (PMID 35806256, 2022). "However, the results were difficult to interpret as the rhodopsin was overexpressed in those mouse lines, which can cause retinal degeneration itself." (PMID 33669941, 2021). "Photoreceptors tightly regulate light-activated Rhodopsin levels and a failure to do so could cause retinal degeneration." (PMID 34714826, 2021). "Therefore, our results support a destabilizing effect of sodium valproate on rhodopsin I307N mutant associated with retinal degeneration." (PMID 34069614, 2021). "In their second study, four groups of heterozygote S334ter-4 rat retinal degeneration model (a mutation identical to the human rhodopsin mutation in RP) were created: 0.2 μg/d FAc-loaded intravitreal drug-delivery implant (IDDI), 0.5 μg/d FAc-loaded IDDI, inactive IDDI, and nonsurgical control." (PMID 34055398, 2021). "Furthermore, SORDD1/2 and HRD1/SYVN1 were also able to prevent retinal degeneration in Drosophila with the G69D (glycine to aspartic acid at amino acid residue 69) rhodopsin mutation." (PMID 34381136, 2021). "Likewise, transgenic rats overexpressing rhodopsin variants causing autosomal dominant retinitis pigmentosa show an early (P20), intermediate (P30), and advanced stages of retinal degeneration (P60)." (PMID 32545533, 2020). "Characterization of retinal degeneration progression in heterozygote P23H rhodopsin-mutated mice." (PMID 32960171, 2020). "Furthermore, rhodopsin has been associated with retinal degeneration, a recently discovered indicator of neurodegenerative diseases." (PMID 32351353, 2020). "Both the rod opsin antagonist activity and in vivo efficacy of YC-001 in a mouse model of bright light-induced retinal degeneration demonstrated the therapeutic potential of this compound in treating retinal degenerations associated with disrupted rhodopsin homeostasis." (PMID 29773803, 2018). "In addition, the SD-OCT findings of the retinal degeneration that occurs in rhodopsin knockout mice, rats with rhodopsin P23H (line 1) mutation (Class 2), rd10 mice, arrestin knockout mice, and RCS rats were reported previously." (PMID 30581855, 2018).
retinal degeneration (continued). "Therefore, Arf4 knockout was predicted to affect rhodopsin localization and likely photoreceptor health, as rhodopsin mislocalization is associated with retinal degeneration." (PMID 28410364, 2017). "Recently, it was reported that light-induced retinal degeneration caused by P23H rhodopsin occurs via cell death by autophagy [49•], supporting the hypothesis that multiple cell death mechanisms cause retinal degeneration." (PMID 28255526, 2017). "By conducting extracellular recording, we examined the electrophysiological properties of V1 in S334ter-line-3 rats (a transgenic model of retinal degeneration developed to express a rhodopsin mutation similar to that found in human retinitis pigmentosa patients)." (PMID 27225415, 2016). "Thus, it is important to understand the mechanisms underlying the folding and trafficking of rhodopsin as well as retinal degeneration caused by misfolded rhodopsin." (PMID 25715730, 2015). "Although ER stress associated with retinal degeneration in some animal models of RHO-ADRP is likely the result of chronic accumulation of misfolded rhodopsin, some studies have demonstrated acute ER stress being triggered within hours following exposure to a toxic chemical, or to light." (PMID 25695253, 2015). "Mutations in the pdh gene provoke light-dependent loss of rhodopsin and retinal degeneration." (PMID 24058333, 2013). "Its functional loss suppresses retinal degeneration in phototransduction mutants by changing the membrane dynamics between late endosomes and lysosomes and by facilitating the degradation of endocytosed rhodopsin." (PMID 23754968, 2013). "Therefore, the accumulation of internalized rhodopsin in late endosomes and impaired endo-lysosomal trafficking clearly causes retinal degeneration in both the norpA and the “granule group” mutant photoreceptors." (PMID 23754968, 2013). "Moreover, Bouse+/0 mRho−/−, Bouse+/0 mRho+/−, and Bouse+/+ mRho+/+ mice all display severe retinal degeneration at an early age, suggesting that the Bouse allele behaves like a mutant rhodopsin gene in mice." (PMID 23185477, 2012). "Thus, LEDGF1-326 is of potential value in treating retinal degenerations associated with P23H rhodopsin." (PMID 21915354, 2011). "P23H rhodopsin, a mutant rhodopsin, is known to aggregate and cause retinal degeneration." (PMID 21915354, 2011). "The purpose of the present study was to determine whether providing high levels of DHA in mice by expressing the fat-1 protein can protect against hereditary retinal degenerations caused by the VPP rhodopsin mutation." (PMID 20806040, 2010). "In addition, P347S mice are very useful because the retinal degeneration in this mouse model is relatively slow compared with that in other RHO-linked transgenic RP lines, such as the Pro23His RHO mouse." (PMID 18034880, 2007). "Interestingly, variants in rhodopsin, Pde6a, Pde6b, Prph2 and Rom1 are associated with inherited retinal degeneration in both humans and mice, and their downregulation may underlie the retinal degenerative phenotype observed in Hbs1ltm1a/tm1a mice." (PMID 38966981, 2024). "Furthermore, a human RHO-knock-in (RHO humanized) mouse model generated previously can simulate pathological changes in RHO-adRP, the retinal degeneration might be caused by any one of the five variants (T17M, G51D, G114R, R135W, and P171R, RHO-5m)." (PMID 37272616, 2023). "In a transgenic mouse model bearing human RHO Pro347Ser mutation, AAVshQ1-mediated suppression of human RHO in combination with replacement with the endogenous mouse gene significantly delayed the retinal degeneration, demonstrated by photoreceptor preservation and improved ERG." (PMID 34395430, 2021). "Examples of rhodopsin accumulation caused by mutations in genes involved in endolysosomal pathways suggest reduced endocytosis in photoreceptors lead to an accumulation of rhodopsin in photoreceptor cells, leading to photoreceptor cell death and ultimately retinal degeneration." (PMID 31117272, 2019).
retinal degeneration (continued). "Docking and fusion of rhodopsin vesicle at distal IS plasma membrane appears dependent on Rab8a, as transgenic expression of a dnRab8a (Rab8aT22N) causes massive rhodopsin-containing vesicle accumulation at the CC base and rapid retinal degeneration in Xenopus larva." (PMID 27529348, 2016). "Rhodopsin mutants causing autosomal dominant retinitis pigmentosa are also phosphorylated at significantly higher levels than in wild-type cells, and rhodopsin dephosphorylation kinetics in the retinal degeneration of P23H rats have been shown to be extremely prolonged, especially in Ser344." (PMID 23901245, 2013). "–31 GRK1 mutations cause Oguchi disease (a night blindness disorder) by preventing proper deactivation of photoactivated RHO, resulting in profoundly delayed rod cell recovery and subsequent retinal degeneration." (PMID 41805095, 2026). "We recently demonstrated with the P23H and G188R rhodopsin mutants that the severity of aggregation observed in vitro is also reflected in vivo and impacts the rate of retinal degeneration." (PMID 39875362, 2025). "Despite these similarities in vitro, the Y178C rhodopsin mutant promoted a more severe retinal degeneration compared to the G188R mutant in vivo in mice." (PMID 39875362, 2025). "While these experiments were conducted in healthy rats, future investigations will examine the device’s performance in retinal degeneration models such as rhodopsin Pro347Leu transgenic (Tg) rabbits." (PMID 40428706, 2025). "In line with this, rhodopsin mis-localization was observed during retinal degeneration in homozygous RhoI255d/I255d and heterozygous RhoI255d/+ mice." (PMID 40738887, 2025). "The role of GDNF in the protection and regeneration of retinal cells has been observed in several studies such as optical nerve crush, rhodopsin knockout mice or retinal degeneration mouse model." (PMID 40594667, 2025). "Samples were collected from mice at 2 weeks of age and the level of rhodopsin transcripts was normalized to that of 18s rRNA or transducin (Gnat1) to account for any retinal degeneration." (PMID 38365903, 2024). "Here, we show that the level of PROTEOSTAT positive cells mirrors the progression and level of photoreceptor cell death, which suggests a potential role for rhodopsin aggregation in retinal degeneration." (PMID 38365903, 2024). "The potential neuroprotective and regenerative properties of electrical stimulation (ES) were studied in rhodopsin knockout mice (Rho−/−), a murine model of inherited retinal degeneration." (PMID 39206091, 2024). "This analysis was used to quantify the POS morphology of wild-type and two inherited retinal degeneration ("retinal degeneration 19" and "rhodopsin knock-out") mouse lines." (PMID 38854587, 2024). "More recent studies show that the retinal degeneration phenotype correlates closely to the amount of RHO overexpression." (PMID 38661530, 2024). "Based on this mechanism, interventions that can reduce rhodopsin aggregation are predicted to reduce the severity of retinal degeneration." (PMID 38365903, 2024). "Approaches that reduce rhodopsin aggregation in vitro appear to reduce retinal degeneration in mouse models, establishing a possible link between aggregation and retinal degeneration." (PMID 38365903, 2024). "Treatment with flavonoids in vitro positively modulated the stability of ligand-free RHO, and in vivo delayed retinal degeneration by reducing UPR and oxidative stress in mouse models bearing the P23H RHO mutation." (PMID 38370034, 2024). "Both homozygous mutant mice exhibited reduced levels of rhodopsin transcripts when normalized to 18S rRNA compared to that in B6 mice, which reflects the retinal degeneration occurring even in young mice." (PMID 38365903, 2024). "Here, the authors show the potential for rhodopsin aggregates to play a role in retinal degeneration." (PMID 38365903, 2024).